STAT3 (signal transducer and activator of transcription 3)
Diseases named in the same sentence as STAT3 in open-access papers (continued):
Sharing a sentence is not in itself a finding about the gene and the disease.
glioma (continued). "Furthermore, TMSB10 may involve glioma immune regulation progression by promoting PD-L1 expression levels via activating STAT3 signaling pathway in glioma cells." (PMID 37275863, 2023). "It has been reported that STAT3 could be a promising target for the treatment of glioma." (PMID 36618071, 2022). "Moreover, STAT3 knockdown impaired the tumorsphere formation of U251-MG glioma cells." (PMID 35562901, 2022). "Importantly, our results also demonstrated that overexpression of STAT3 rescues the TMEM158 knockdown-mediated proliferation, migration, invasion, and EMT process, indicating that TMEM158 promotes the proliferation, migration, and invasion of glioma cells by activating STAT3 signaling." (PMID 34992215, 2022). "Thus, STAT3 has a significant impact on glioma immunosuppression." (PMID 37786890, 2022). "Consequently, we and others previously demonstrated that targeting STAT3 by upstream signaling inhibitors of the STAT3 pathway or by genetic depletion decreases glioma cell proliferation and migration in vitro and prolongs overall survival of tumor-bearing mice in vivo." (PMID 35053502, 2022). "Therefore, STAT3 is apparently an attractive target for the treatment of glioma." (PMID 36618071, 2022). "Indeed, IL6 signaling through STAT3 is required for glioma development in a preclinical model." (PMID 36046049, 2022). "To investigate whether NC inhibits the expression of stem cell‐related markers through the modulation of JAK2/STAT3 signaling, we used WP1066 to inhibit JAK2/STAT3 signaling and further studied the effect of JAK2/STAT3 activity on the expression of stem cell markers in glioma cells." (PMID 33788424, 2021). "Moreover, the self-renewal of glioma-initiating cells is achieved by the LIF/STAT3 signaling." (PMID 34729101, 2021). "Additionally, STAT3 can bind to the first intron of the miR-34a genomic region to suppress miR-34a expression, while miR-34a acts as a tumour suppressor in hypoxia-induced glioma cells." (PMID 34425834, 2021). "Therefore, the JAK2/STAT3 signaling may be involved in fraxetin-mediated antitumor effects on glioma." (PMID 33959183, 2021). "Therefore, further exploration of noncoding RNAs related to STAT3 expression and activation in glioma may provide an avenue for STAT3-targeted glioma treatment." (PMID 34425834, 2021). "Moreover, the inhibitory effect of NC in glioma cells may be achieved through altered JAK2/STAT3 pathway activity." (PMID 33788424, 2021). "In addition, we evaluated the activity of JAK2/STAT3 signaling in glioma." (PMID 33959183, 2021). "Furthermore, fraxetin was able to effectively inhibit the JAK2/STAT3 signaling in glioma." (PMID 33959183, 2021). "Therefore, we infer that the low expression of miR-2276-5p leads to the differential expression of RAB13, and RAB13 may promote glioma angiogenesis through the JAK/STAT3 signaling pathway, leading to tumor proliferation and poor prognosis." (PMID 34141710, 2021). "Moreover, recent studies have suggested that STAT3 and P-STAT3 may play similar functions in various tumors, including gliomas." (PMID 34976781, 2021). "Therefore, STAT3 has been considered an ideal therapeutic target in glioma." (PMID 34425834, 2021). "In glioma, miR-506 may exert carcinostatic activities by targeting STAT3." (PMID 33336050, 2020). "Our data demonstrate that ACYP2 functions as an oncogene in glioma through activating c-Myc and STAT3 signals via the regulation of intracellular Ca2+ homeostasis, and indicate that ACYP2 may be a potential therapeutic target and prognostic biomarker in gliomas." (PMID 32517717, 2020). "Furthermore, ObR expression in glioblastoma cells imparts progenitor/stem cell-like properties through STAT3-mediated upregulation of the pluripotency-associated SOX2/OCT4 signaling axis, which underlies the self-renewal properties of glioma cells and resistance to drugs such as temozolomide." (PMID 33316976, 2020).
glioma (continued). "Thus, we suppose that ACYP2 may promote phosphorylation and activity of STAT3 through modulating Ca2+/calpain signaling axis, contributing to malignant progression of glioma cells." (PMID 32517717, 2020). "What could be the significance of STAT3 activation in glioma foci?" (PMID 32218467, 2020). "Furthermore, STAT3 expression is correlated with the highly aggressive mesenchymal subtype of glioma that is particularly resistant to conventional therapy and is known to regulate stemness in glioma cells." (PMID 30857197, 2019). "Furthermore, miR-148a delivered by exosomes may promote cancer cell proliferation and metastasis by targeting CADM1 to activate STAT3 pathway, which suggests a predictor and therapeutic target role of exosomal miR-148a in glioma patients." (PMID 31052326, 2019). "Using this approach we could show that LPPs loaded with Stat3-siRNA inhibit proliferation of glioma cells in the absence of unspecific toxicity in vitro, significantly limit tumor growth in vivo and improve the overall survival of glioma-bearing mice." (PMID 30857197, 2019). "At present, glioma cell lines are poor disease models, missing important genetic and phenotypic characteristics, further indicating that patient-derived cells may be the most suitable cell population to investigate STAT3 inhibitors." (PMID 31698775, 2019). "Moreover, anti-VEGF therapy was demonstrated to elevate STAT3 expression in glioma patients and STAT3 inhibitors could be therefore used to ameliorate the anti-angiogenic treatment schemes." (PMID 31698775, 2019). "Furthermore, in our rescue experiments, we explored whether the downregulation of STAT3 alters the biological function of glioma cells by inducing FOXP1." (PMID 30134017, 2018). "In a word, these results yielded that STAT3 and FOXP1 may be underlying therapeutics for glioma." (PMID 30134017, 2018). "Wnt/β-catenin, MAPK/ERK, PI3K/AKT and STAT3 signaling are highly activated in glioma, so it is conceivable that simultaneous pharmacological inhibition of all these signaling pathways might be the most effective therapeutic strategy for the prevention and treatment of glioblastoma." (PMID 28877265, 2017). "However, the mechanism that STAT3 promotes glioma malignant behaviours remains poorly understood." (PMID 28470949, 2017). "The HSP70/SR-A1 pathway may inhibit STAT3/6 signaling in TAMs to slow glioma progression." (PMID 27367025, 2016). "However, it does not exclude the possibility that other signal pathways like JAK/STAT pathway might also be involved in TRPM7-mediated astrocyte proliferation, just as TRPM7 channel regulates glioma stem cells through STAT3 and Notch signaling pathways." (PMID 25799367, 2015). "Therefore, the presence of elevated STAT3 activity in human gliomas may be a factor in efficacy of oHSV." (PMID 23936533, 2013). "Therefore, genetic manipulation of STAT3 altered oHSV-mediated cytptoxicity of glioma cells." (PMID 23936533, 2013). "It has also been reported that an adenovirus-vector carrying basic fibroblast growth factor siRNA reduced STAT3 phosphorylation and ultimately resulted in the collapse of the mitochondrial membrane potential and the induction of mitochondrial-related apoptosis in U251 glioma cells." (PMID 23483946, 2013). "Though STAT3 activation appears to play a key role in generating and perpetuating the M2-type TAMs in gliomas, it is unclear whether a single dominant molecule or a complex network of molecules is responsible for the immunosuppressive phenotype of glioma TAMs." (PMID 23737783, 2013). "Furthermore, it is unknown if the withdraw of VEGF signaling inhibitors would result in the down regulation of p-STAT3 expression in the glioma microenvironment." (PMID 23013619, 2012). "In summary, convallatoxin attenuates glioma cells’ proliferation, migration, invasion, and angiogenesis via blocking the JAK/STAT3 signaling pathway." (PMID 40321161, 2025).
glioma (continued). "In glioma, the JAK/STAT3 pathway contributes to tumor progression and resistance to conventional therapies, highlighting its potential as a therapeutic target." (PMID 40321161, 2025). "In this study, the anti-proliferative and anti-angiogenesis effects of convallatoxin were investigated in human glioma cell lines U251MG and A172, along with its role in migration, invasion, and regulation of the JAK/STAT3 signaling pathway." (PMID 40321161, 2025). "Nuclear-localized SIRT6 is notably downregulated in glioma and acts as a tumor suppressor through various mechanisms, including inhibition of the JAK2/STAT3 and NOTCH3 signaling pathways." (PMID 40710366, 2025). "IL-6 can bind to IL-6R on the surface of glioma cells and activate the downstream JAK2/STAT3 signaling pathway, enabling them to acquire the stemness and invasiveness phenotype." (PMID 40243478, 2025). "STAT3 and NF-ĸB have been found to directly regulate the expression of c-Myc and MMP9 in glioma cells." (PMID 40759869, 2025). "By inactivation of the JAK/STAT3 signaling axis, activin receptor-like kinase 4 (ALK4) represses cell growth and migration in glioma." (PMID 40321161, 2025). "In glioma models, resveratrol can enhance temozolomide (TMZ) responses via STAT3 down-regulation and induce apoptosis when combined with TMZ." (PMID 41463173, 2025). "The relationship between p-STAT3 expression and the WHO grade of glioma was evaluated using immunohistochemistry (IHC) and tissue microarray analysis." (PMID 40265014, 2025). "Ribosomal protein L34 (RPL34) knockdown represses glioma cells’ growth and migration via inhibiting the JAK/STAT3 pathway." (PMID 40321161, 2025). "We highlight signaling axes such as IL-6/STAT3, NF-κB, and TGF-β that connect immune dysregulation to epigenetic instability and the emergence of glioma-initiating cells." (PMID 41403936, 2025). "Through crosstalk with STAT3, MAPKs, and PI3K/Akt, NF-κB amplifies glioma stem-like cells, their invasion, and resistance to radiation and temozolomide." (PMID 41463173, 2025). "Mechanistic studies indicate that B7-H3 promotes glioma cell proliferation and invasion via the JAK2/STAT3/Slug pathway and by inducing epithelial–mesenchymal transition (downregulating E-cadherin and upregulating MMP-2/9)." (PMID 40867203, 2025). "Activation of STAT3 and Notch pathways regulates ALDH1 genes in glioma stem cells (GSCs), suggesting promising targets for glioma therapy." (PMID 40806720, 2025). "Glioma-released exosomal miR-3591-3p promotes macrophage to the M2 phenotype by targeting CBLB to activate the JAK2/PI3K/Akt/mTOR and STAT3, thereby promoting glioma progression." (PMID 40443670, 2025). "In particular, the activation of JAK/STAT3 by BACE1 contributes to a feedback loop that perpetuates a pro-tumorigenic and immune-evasive environment within the glioma TME." (PMID 41479886, 2025). "Immune-related pathways such as TNF signalling (IDH3B/G, MDH1, ACO2, SDHA, OGDHL) and JAK/STAT3 (PIAS2/3, PTPN2, AKT1/2, MCL1, CISH, AOX1) signalling are enriched in gliomas and play a critical role in their progression." (PMID 41007296, 2025). "The results showed that the JAK/STAT3 signaling pathway, STAT5 signaling pathway, nuclear factor-κB activation, and apoptosis significantly enriched glioma phenotypes with high LINC00324 expression." (PMID 38530810, 2024). "SRPK1 promotes the proliferation, migration, and invasion of gliomas through the activation of the Wnt/β-catenin and JAK-2/STAT-3 signaling pathways." (PMID 38397980, 2024). "Studies have shown that in primary glioma models (U251 and SHG-44), XHP treatment alone downregulated POU4F1 and STAT3 levels and increased LDH release and IL-1β and IL-18 levels, and the apoptosis-associated factor NLRP3 was activated." (PMID 38957318, 2024). "Compared to the normal glioma cell line HA1800, quantitative PCR (qPCR) analysis revealed EZH2 and STAT3 were higher in U87, H4, and A172 (glioma cell lines)." (PMID 39069522, 2024).
glioma (continued). "The results showed that upregulated TCAF2 enhanced migration/invasion properties in glioma cultures through an EMT-like process and STAT3 activation." (PMID 38019450, 2024). "Simultaneously, we demonstrated that inhibiting p-STAT3 through EZH2 enhances NLRP3 inflammasome activity, promoting glioma pyroptosis and the expression of inflammatory factors IL-1β and IL-18." (PMID 39069522, 2024). "Altogether, our results indicate that KIAA0040 promotes glioma cell migration and invasion through the JAK2/STAT3 pathway activation." (PMID 38661644, 2024). "In glioma and melanoma, IGFBP2 facilitates the nuclear accumulation of EGFR, thereby activating STAT3." (PMID 38918360, 2024). "In glioma cells, PVT1 recruits COPS5 to deubiquitinate and stabilize TRIM24, leading to the activation of STAT3 signaling and the induction of malignant biological behaviors." (PMID 39160596, 2024). "The results showed that the mRNA expression levels of STAT3 (P < 0.01), IL-6 (P < 0.01), and TNF-α (P < 0.01) were significantly increased in glioma samples compared with paracancerous tissues." (PMID 38495483, 2024). "Functional assays showed that KIAA0040 enhances glioma growth, migration and invasion by activating the JAK2/STAT3 pathway." (PMID 38661644, 2024). "Our earlier studies uncovered a pivotal event in glioma development- the activation of FOSL1, an integral member of the AP-1 transcription factor family, by the STAT3 gene." (PMID 38856747, 2024). "Consistently, we demonstrate that KIAA0040 overexpression promotes glioma cell migration and invasion, which is possibly mediated via the JAK2/STAT3 pathway activation." (PMID 38661644, 2024). "Signalling crosstalk between the NF-κB and STAT3 was apparent in cell line models of TSC, which is a feature shared in cancer, including glioma." (PMID 39070657, 2024). "XHP promotes cellular pyroptosis by regulating the POU4F1/STAT3/NLRP3 pathway and inhibits glioma malignant progression." (PMID 38957318, 2024). "Our results collectively suggested that isocuB inhibited glioma cell proliferation, migration, and invasion, and induced apoptosis via the PI3K/AKT, MAPK, and STAT3 pathways." (PMID 38835342, 2024). "This research suggests a new treatment strategy for gliomas, but more studies are needed to confirm these results and investigate targeting the KIAA0040‐JAK/STAT3 axis for therapy." (PMID 38661644, 2024). "In glioma cells, TRIM24 recruits STAT3 as a transcriptional co-activator, stabilizing STAT3-chromatin interactions, which activates STAT3 downstream signaling and amplifies EGFR-driven cell proliferation." (PMID 39160596, 2024). "Through the co-culture of PBMC and glioma cells, our data showed that down-regulation of c-MET in Ln299 significantly decreased the activation of STAT3 and the expression level of PDL1 in this cell." (PMID 38352883, 2024). "Specifically, our previous research highlighted how STAT3 triggers FOSL1 transcription by binding to the two GAS elements within the FOSL1 promoter, thereby enhancing glioma stemness." (PMID 38856747, 2024). "SRPK1 promotes the proliferation, migration, and invasion of gliomas by activating the Wnt/β-catenin and JAK-2/STAT-3 signaling pathways." (PMID 38397980, 2024). "Cell experiment showed that modulation of the JAK2/STAT3 pathway by CTR9 was found to promote proliferation, migration, and invasion of glioma cells." (PMID 37766864, 2023). "The potential mechanisms involving STAT3 activation mediating TMEM158-driven glioma progression have also been identified, and the inhibitory effect of TMEM158 downregulation on glioma growth has been confirmed." (PMID 36755318, 2023). "Activated NF-κB then stimulates STAT3, CEBPB, and TAZ by phosphorylation, enhancing the invasion, tumorigenesis, and therapeutic resistance of gliomas." (PMID 38072944, 2023).
glioma (continued). "As a transcriptional co-activator of STAT3, TRIM24 leads to the activation of STAT3 downstream signaling in response to EGFR in glioma cells, ultimately supporting the stem cell-like phenotype." (PMID 36674511, 2023). "Hyperactivated STAT3 has been demonstrated to modulate the behavior of gliomas and promote ADR and the STAT3 inhibitor pacritinib in combination with temozolimide has been shown to be effective in glioblastoma overwhelming STAT3/miR-21/PDCD4 signaling." (PMID 36902166, 2023). "We will delve into the current literature regarding the role of autophagy in glioma pathogenesis by exploring the major pathways of JAK2/STAT3 and PI3K/AKT/mTOR and summarizing the current therapeutic interventions and strategies for glioma treatment." (PMID 37998723, 2023). "In glioma, IGFBP2 forms a complex with the EGFR leading to EGFR accumulation inside the nucleus and induction of STAT3 transactivation." (PMID 37029430, 2023). "IL-11 secreted by microglia activates STAT3 signaling pathways, leading to increased MYC expression, and MYC overexpression transforms glioma cells into a stem cell state, thereby enhancing tumorigenicity and TMZ resistance." (PMID 37700840, 2023). "Based on our previous findings that TRPM7 enhances glioma stemness by triggering STAT3 activation, in the present study, we will investigate the mechanisms by which TRPM7/STAT3/FOSL1 regulatory axis drives stemness and growth in glioma." (PMID 37642779, 2023). "In gliomas, JAK-1 and STAT-3 appear to be the major proteins that are altered in the JAK/STAT pathway." (PMID 37626776, 2023). "Crosstalk and synergistic effects of STAT3 and HIF-1 signaling pathways have also been observed in several neurological disorders, such as glioma and pericyte glucose deprivation." (PMID 37373133, 2023). "STAT3/miR-182-5p/tumor suppressor protein-8 (PCDH8) signaling also promotes the migration and invasion of glioma cells." (PMID 36923251, 2023). "Specifically, it showed the ability to inhibit the expression of phosphorylated STAT3 and its downstream genes (e.g., Survivin, Cyclin D1, COX-2 and cMyc) in glioma cell lines." (PMID 36923251, 2023). "Elevated levels of phosphorylated STAT3 (active form of STAT3) were observed in the WG9, WG10, WG13, WG14, and WG18 primary glioma cell lines." (PMID 36900355, 2023). "TRPM7 activates the JAK2/STAT3 signaling pathway leading to glioma aggravation, as there is crosstalk between this pathway and ALDH1 and CD133, two glioma stemness markers, suggesting a role of TRPM7 in glioma stem cells." (PMID 37762011, 2023). "Mast cells suppress the signal transducer and activator of transcription 3 (STAT3) pathway by downregulating glycogen synthase kinase 3β (GSK3β), thereby diminishing the proliferation, migration, and invasion of glioma cells." (PMID 37662954, 2023). "In our study, we found that STAT3 regulates downstream gene target, FOSL1, which is closely related to glioma stemness and therefore facilitates gliomagenesis." (PMID 37642779, 2023). "In vitro, the application of the STAT3 ODN-decoy to treat the malignant U251 and A172 glioma cells resulted in cell proliferation inhibition, cell cycle arrest at the G0/G1 phase, and induction of cell apoptosis." (PMID 38067351, 2023). "HSP70, an endogenous ligand of SR-A1, induces the inhibition of STAT3 and STAT6 to promote M1 TAM polarization, thereby suppressing the progression of glioma." (PMID 37759870, 2023). "Combination treatment with the chemotherapeutic agent temozolomide and an inhibitor of ROS1, JAK2, or a downstream target of STAT3, demonstrated antitumor effects against KLC1-ROS1 fusion-expressing glioma cells." (PMID 38201436, 2023). "High level of ARSD promoted the development of glioma by regulating M2 macrophage infiltration and JAK2/STAT3 pathway." (PMID 37766864, 2023).